RNU6-1322P (RNA, U6 small nuclear 1322, pseudogene)
Gene: Small nuclear RNA gene on chromosome 7 (105,332,790 to 105,332,896, forward strand). Ensembl gene ENSG00000201179.
Homologues: Orthologues: chimpanzee U6 (100% identical), dog U6 (77% identical), guinea pig U6 (75% identical), rabbit U6 (74% identical), dog U6 (64% identical). Paralogues in human: RNU6-774P (89% identical), RNU6-38P (88% identical), RNU6-1011P (87% identical), RNU6-1309P (87% identical), RNU6-33P (87% identical), RNU6-468P (87% identical), RNU6-1 (86% identical), RNU6-2 (86% identical), RNU6-21P (86% identical), RNU6-28P (86% identical), RNU6-39P (86% identical), RNU6-3P (86% identical), and 1288 more.